U2 (U2 spliceosomal RNA )
Gene: Small nuclear RNA gene on chromosome 14 (75,270,700 to 75,270,780, reverse strand). Ensembl gene ENSG00000283519.
Homologues: Paralogues in human: RNU2-41P (64% identical), RNU2-55P (64% identical), U2 (63% identical), RNU2-28P (62% identical), RNU2-42P (62% identical), RNU2-10P (60% identical), RNU2-53P (60% identical), RNU2-34P (59% identical), RNU2-72P (59% identical), RNU2-22P (58% identical), RNU2-58P (58% identical), RNU2-60P (58% identical), and 63 more.